GNE (glucosamine (UDP-N-acetyl)-2-epimerase/N-acetylmannosamine kinase)
Diseases named in the same sentence as GNE in open-access papers (continued):
Sharing a sentence is not in itself a finding about the gene and the disease.
diaphragmatic hernia (1 paper, 2020). A congenital or acquired weakness or opening in the diaphragm which allows abdominal contents to protrude into the chest cavity; congenital diaphragmatic hernias are caused when the embryonic diaphragm fails to fuse. "Patient 125 with c.1807G > C in the GNE (NM_0011282272) showed facial dysmorphism, congenital heart defect, vertebral anomaly, diaphragmatic hernia, and skeletal dysplasia." (PMID 32901917, 2020).
galactosemia (1 paper, 2025). "Some researches showed that there is a certain functional connection between GNE and galactose-related enzymes in Aeromonas hydrophila, though we have not found relevant researchs that galactosemia-related genes have functional interactions with the patient's GNE mutations." (PMID 40687627, 2025).
gastric cancer (1 paper, 2022). A primary or metastatic malignant neoplasm involving the stomach. "Results indicated that a low expression of GNE was remarkably associated with poor prognosis in gastric cancer patients." (PMID 36429052, 2022). "In order to investigate the differential expression of GNE in gastric cancer, we analyzed the TCGA_STAD dataset (Stomach Adenocarcinoma dataset from The Cancer Genome Atlas) based on the GEPIA database and the results showed that the expression of GNE increased significantly in the tumor group." (PMID 36429052, 2022). "In summary, our model collaborating GNE expression and clinicopathological features proved that incorporating GNE could help to achieve superior prediction for lymph node metastasis in early gastric cancer." (PMID 36429052, 2022). "Next, we performed real-time PCR analysis to examine the GNE expression in early gastric cancer clinical samples with or without LNM." (PMID 36429052, 2022). "The results showed that early gastric cancer cases with LNM presented lower GNE protein expression levels in comparison with those without LNM, which was consistent with the result of real-time PCR." (PMID 36429052, 2022).
myotonic dystrophy type 1 (1 paper, 2013). Steinert disease, also known as myotonic dystrophy type 1, is a muscle disease characterized by myotonia and by multiorgan damage that combines various degrees of muscle weakness, arrhythmia and/or cardiac conduction disorders, cataract, endocrine damage, sleep disorders and baldness. "Remudy has been developing Japanese registries for other neuromuscular diseases including glucosamine (UDP-N-acetyl)–2-epimerase/N-acetylmannosamine kinase (GNE) myopathy and myotonic dystrophy type 1 (DM1)." (PMID 23601510, 2013).
nephrotic syndrome (1 paper, 2012). A collection of symptoms that include severe edema, proteinuria, and hypoalbuminemia; it is indicative of renal dysfunction. "In conclusion, the GNE V572L mutation caused the hyposialylation of renal glycoproteins such as PC, resulting in glomerular filtration barrier failure and nephrotic syndrome-like phenotypes." (PMID 22253810, 2012).
neuropathy (1 paper, 2024). A disorder affecting the nervous system that manifests with pain, tingling, numbness, and/or muscle weakness. "Lower extremity MRI results taken at 2-year intervals in the affected man (Myo-41) with both symptoms of myopathy and neuropathy showed a pattern of muscle involvement associated with GNE mutations." (PMID 38674419, 2024).
renal failure (1 paper, 2021). "GNE knockout mice were found to be embryonically lethal and GNE transgenic mice showed variations in the phenotype with renal failure." (PMID 33816461, 2021).
vacuolar myopathy (1 paper, 2015). "Other vacuolar myopathy related genes previously ruled out in these sporadic patients by Sanger sequencing were: GNE and ANO5 for patient 1s, GNE for 2s, GNE, ANO5 and MYH7 for 3s and GNE for 4s." (PMID 26205529, 2015).
ZIKV infection (1 paper, 2019). "GNE knockout in mice causes early embryonic lethality, which limits the in vivo investigation of the role of sialic acid in ZIKV infection in mice." (PMID 30898036, 2019).
myopathy (41 papers, 2008 to 2025). A disease of the muscle in which the muscle fibers do not function properly. "Keeping both scaffolds in place at this point improves the chances of creating small-molecule modulators of GNE activity that work, especially considering complex clinical challenges associated with GNE myopathy." (PMID 41339784, 2025). "An early study revealed that GNE mutations were most frequent in genetically diagnosed Korean patients with recessive myopathy, either in compound heterozygous or homozygous states." (PMID 38674419, 2024). "A rare muscle disease, GNE myopathy is caused by mutations in the GNE gene involved in sialic acid biosynthesis." (PMID 37568154, 2023). "The present study describes the GNE V727M–specific associated coexpressed gene network in HIBM myopathy." (PMID 36980840, 2023). "Nevertheless, large rearrangements in the GNE gene have been reported several times, and the possible occurrence of CNVs should be considered in cases of myopathy with a heterozygous variant in the GNE gene." (PMID 36360228, 2022). "Inherited in an autosomal recessive manner, patients with GNE myopathy carry mutations in the GNE gene which affect the sialic acid synthesis pathway." (PMID 36330422, 2022). "GNE myopathy is caused by a defect in GNE, and hyposialylation is a key factor in the pathomechanism of GNE myopathy." (PMID 33225515, 2021). "Currently, a definite diagnosis of GNE myopathy mainly relies on genetic testing, confirmed by evidence of compound heterozygous or homozygous mutations in the GNE gene." (PMID 34676965, 2021). "GNE myopathy is caused by mutations in the UDP-N-acetylglucosamine-2-epimerase/N-acetylmannosamine kinase(GNE) gene and is clinically characterized by progressive weakness and atrophy of the lower-limb muscles with quadriceps sparing." (PMID 33031330, 2020). "The majority of the variants detected in GNE were missense variants located throughout the GNE gene, suggesting an important role of missense changes in causing GNE-myopathy in people of Indian subcontinent origin." (PMID 33250842, 2020). "GNE myopathy severity significantly varies in all cohorts, with 20% of variability explained by the GNE mutation." (PMID 30842975, 2019). "GNE myopathy is caused by the mutations in the UDP‐N‐acetylglucosamine 2‐epimerase/N‐acetylmannosamine kinase gene (GNE), which encodes the bifunctional enzyme catalysing the first two rate‐limiting steps in sialic acid biosynthesis." (PMID 30160005, 2018). "A homozygous missense mutation, c.1627G>A (p.V543M) in the GNE gene co‐segregates with the myopathy present in this family." (PMID 30160005, 2018). "BJAB K20 cells expressing wild-type GNE or either GNE myopathy-associated mutant (D179V or M712T) had similar, high levels of intracellular sialic acid despite the fact that both mutations are known to result in reduced enzymatic activity." (PMID 28424265, 2017). "The experiments reported here were initiated with the goal of exploring how mutations to GNE lead to GNE myopathies." (PMID 28424265, 2017). "We introduced expression of wild-type GNE or a mutant form of GNE, GNE D176V, which harbors a GNE myopathy-associated mutation to the epimerase domain, or GNE M712T, which harbors a GNE myopathy-associated mutation to the kinase domain." (PMID 28424265, 2017). "In this study, we present two Turkish sisters with progressive myopathy and describe a novel mutation in the GNE gene." (PMID 27298745, 2016). "The cause of GNE myopathy is a mutation in the UDP-N-acetylglucosamine 2-epimerase/N-acetylmannosamine kinase (GNE) gene." (PMID 26968811, 2016). "In the same vein, the other classical hereditary inclusion body myopathy is caused by UDP-N-acetylglucosamine-2-epimerase/N-acetylmannosamine kinase (GNE) gene mutation (leading to quadriceps-sparing myopathy)." (PMID 25579751, 2015). "GNE encodes for a key enzyme in sialic acid biosynthesis and the myopathy is associated with the formation of autophagic vacuoles." (PMID 25579751, 2015).
myopathy (continued). "GNE myopathy is a slowly progressive autosomal recessive myopathy caused by mutations in the GNE (glucosamine (UDP-N-acetyl)-2-epimerase/N-acetylmannosamine kinase) gene." (PMID 25303967, 2014). "Mutations of the UDP-N-acetylglucosamine-2-epimerase/N-acetylmannosamine-kinase (GNE)-gene are causally related to GNE myopathy." (PMID 23496965, 2013). "This also indicates that altered lincRNAs may mediate the interaction between molecules, further implicating the GNE mutation role in the regulation of key pathways, thereby leading to myopathy." (PMID 36980840, 2023). "In conclusion, homozygotes for c.620A>T rarely develop myopathy, while symptoms occur in compound heterozygotes, probably because of mildly decreased sialylation, due to partial defects in oligomerization and product trafficking by the mutated GNE protein." (PMID 36526893, 2022). "Further, Gne knock out cells might unravel the mechanism that leads from GNE mutation to the myopathy." (PMID 36237634, 2022). "Notably, tissue hyposialylation due to deficits in GNE activity leads to age-related neuronal loss and enhances oxidative stress in the skeletal muscle of patients with GNE myopathy." (PMID 33340902, 2021). "We have reported the case of a GNE myopathy patient with compound heterozygous GNE gene mutations." (PMID 33031330, 2020). "Indeed, GNE mutations can result in two human disorders, GNE myopathy or sialuria." (PMID 29720219, 2018). "In relation to muscle health, 6′-SL has also been demonstrated to ameliorate myopathic phenotypes, such as muscle weight and locomotor activity, in symptomatic bifunctional UDP-N-acetylglucosamine 2-epimerase/N-acetylmannosamine kinase (GNE) myopathy." (PMID 39203737, 2024). "Therefore, although mutations in the GNE gene have been primarily described as being associated with myopathies, the neurological involvement associated with GNE mutations may be an underdiagnosed pathology and may influence clinical symptoms and disease progression." (PMID 38674419, 2024). "This form of myopathy results from mutations in the GNE gene present on chromosome 9p13-p12, which codes for a bifunctional enzyme (UDP-GlcNac epimerase/ManNac Kinase; GNE/MNK)." (PMID 36980840, 2023). "Since the available GNE Myopathy in vivo mouse models and in vitro cell culture models are less informative than expected, additional models where the effect of GNE mutation could be more dramatic are needed to determine the function(s) of GNE specifically in muscle." (PMID 36237634, 2022). "GNE myopathy is caused by biallelic variants in the GNE gene, which encodes a bifunctional enzyme, UDP-N-acetylglucosamine 2-epimerase/N-acetylmannosamine kinase (GNE/MNK kinase), that catalyzes critical steps in sialic acid (SA) biosynthesis." (PMID 36526893, 2022). "Even though sialic acid is very crucial for cell functioning, therapeutic treatment of GNE myopathy cannot be fulfilled just by restoration of sialylation as GNE is involved in signaling that modulates cell migration." (PMID 33816461, 2021). "As more than 190 mutations in GNE have been identified worldwide, complete sequencing of the GNE is necessary for diagnosis of GNE myopathy." (PMID 30374284, 2018). "In 2012, Mitrani-Rosenbaum and co-workers applied a gene therapeutic approach as an interventional concept to treat GNE myopathy: AAV8 viral vectors carrying wild type human GNE cDNA were able to transduce murine and human muscle cells carrying GNE mutations." (PMID 29720219, 2018). "Cho and co-workers performed a study utilizing another in vivo model of GNE myopathy, the Gne−/−hGNEV207L-Tg mice." (PMID 29720219, 2018). "The combined data suggest that myonuclei are involved in the formation of rimmed vacuoles in GNE myopathy and that mutant GNE in myonuclei seems to play some role in this process." (PMID 29720219, 2018).
myopathy (continued). "Because of the key role of GNE as a regulator of sialic acid production, much work on GNE myopathy focused on the potential for changes in sialylation of cell surface glycoproteins and glycolipids (7, –, 10)." (PMID 28424265, 2017). "This suggests that various HIBM myopathy-specific GNE mutations could induce downstream pathogenic effects by deregulating the COL6a3 and coexpressed gene signature in HIBM myopathy." (PMID 36980840, 2023). "The treatment of GNE myopathy mainly focuses on a sialic acid deficiency caused by a mutation in the GNE gene, but it has not achieved the expected effect." (PMID 35904705, 2022). "GNE myopathy is caused by a mutation in the GNE gene, which encodes a bifunctional enzyme with UDP-N-acetylglucosamine 2-epimerase activity in the amino-terminal region and N-acetylmannosamine kinase activity in the carboxy-terminal region." (PMID 35904705, 2022). "The exact pathomechanism of GNE myopathy is still unknown but is most likely attributable to aberrant protein sialylation, identified as a common result of decreased GNE enzyme activity." (PMID 34676965, 2021). "The aim of the study is to explore cohort-based studies to test the hypothesis that GNE genotype influences GNE myopathy disease severity." (PMID 30842975, 2019). "Of note, biallelic GNE missense mutations in other patients with GNE myopathy appeared to not affect GNE mRNA expression, which was not previously reported." (PMID 28717665, 2017). "Here we use BJAB K20 cells that do not express GNE to examine the effects of GNE myopathy-associated mutations on N-linked glycan structure and function." (PMID 28424265, 2017). "GNE myopathy is caused by mutations in the GNE gene (GenBank Accession No. NP_005467.1) that encodes the bifunctional enzyme UDP-N-acetylglucosamine 2-epimerase/N-acetylmannosamine kinase that catalyzes two critical steps in sialic acid synthesis." (PMID 23472144, 2013). "Accordingly, mice with a knockout of the GNE gene develop a myopathy with features of GNE myopathy." (PMID 23496965, 2013). "UDP-N-acetylglucosamine-2-epimerase/N-acetylmannosamine kinase (GNE) myopathy is an early adulthood onset, autosomal recessive, rare myopathy with a prevalence of ~1–9/1,000,0001." (PMID 36085325, 2022). "DYSF gene is much larger than some of the other genes such as GNE and CAPN3, the other two most prevalent myopathy forms in this study." (PMID 33250842, 2020). "GNE, DYSF, and CAPN3 are the three major genetic contributors to these myopathies in the Indian subcontinent." (PMID 33250842, 2020). "In conclusion, this study emphasizes considering genomic rearrangement/deep intronic and CNV analysis in the GNE gene, with emphasis on the exon 2 containing region, in patients with characteristic features of GNE myopathy, in which no biallelic pathologic GNE variants could be identified." (PMID 28717665, 2017). "GNE myopathy pathophysiology has not been elucidated yet, in spite of the knowledge accumulated on GNE protein function as a bifunctional key enzyme in the biosynthesis pathway of sialic acid." (PMID 36237634, 2022). "Moreover, our study found that metformin can restore damaged autophagic flux, enhance the vitality of fibroblasts from patients with UDP-N-acetylglucosamine 2-epimerase/N-acetylmannosamine kinase (GNE) myopathy, reduce the rate of apoptosis, and thus play a protective role in GNE myopathy." (PMID 37928155, 2023). "The D176V GNE point-mutant mice exhibit myopathic features, but not renal disorders, while the M712 T point-mutant mice display severe renal hematuria and neonatal lethality, but not myopathy." (PMID 22253810, 2012). "Interestingly, the Gne−/−hGNEV572L-Tg animals moreover exhibit hyposialylation and intracellular amyloid deposition before the characteristic rimmed vacuoles can be detected, suggesting that autophagy might be a downstream effect to hyposialylation and amyloid deposition in GNE myopathy." (PMID 29720219, 2018).
tumor (16 papers, 2013 to 2025). "Because extensive sialylation is associated with tumor cells and metastasis, GNE inhibitors can be used as anticancer drugs." (PMID 26980148, 2016). "GNE encodes a key enzyme in sialic acid biosynthesis, a process that is often upregulated in tumor development." (PMID 27330572, 2016). "Combining GNE expression with traditional risk factors, including tumor size and differentiation degrees, could generate a better model for predicting LNM in EGC patients." (PMID 36429052, 2022). "GNE is widely expressed in mammalian cells, with the highest expression level in tumor cells and liver cells." (PMID 40665355, 2025). "To specifically assess the role of sialoglycan expression in cancer cells, we injected SigEΔLysM and SigEWT mice with B16F10 and B16F10 GNE knockout (KO) tumor cells." (PMID 38448555, 2024). "GNE expression as well as localization, tumor size, intravascular tumor thrombi and Lauren’s classification were further identified as independent predictive factors for LNM." (PMID 36429052, 2022). "To further corroborate this result, we used MC38 GNE-KO tumor cells as a genetic model of desialylation." (PMID 36322632, 2022). "Expression of GNE in UMRC2−/+VHL cells validated the changes found using the microarray, with reduced expression of GNE being seen in VHL transfectants and GNE levels were also upregulated in a significant proportion of tumours compared to normal renal tissue." (PMID 23970118, 2013). "In particular, miR-550a-5p was shown to promote the proliferation and migration of HCC both in vitro and in vivo in a xenograft tumor model by targeting glucosamine (UDP-N-acetyl)-2-epimerase/N-acetylmannosamine kinase (GNE) via the Wnt/β-catenin signaling pathway." (PMID 37958352, 2023). "Furthermore, in matched normal kidney cortex and conventional RCC tissues, GNE was found to be upregulated in 6/8 tumours." (PMID 23970118, 2013). "We found that the sialic acid-donor synthesis pathway is particularly upregulated in PDAC, observing an increased expression of GNE, NANP and SLC35A1, suggesting a general increase of sialylation in the tumour." (PMID 33627655, 2021). "Tumor growth was not significantly different among SigEΔLysM and SigEWT mice injected with B16F10 GNE KO cells and mice injected with the B16F10 wild-type cells, suggesting a Siglec-E-dependent effect in our model involving sialylated glycans on cancer cells." (PMID 38448555, 2024).